TLR4 (toll like receptor 4)
Diseases named in the same sentence as TLR4 in open-access papers (continued):
Sharing a sentence is not in itself a finding about the gene and the disease.
nephritis (13 papers, 2013 to 2025). Inflammation of renal tissue. "& A. Huet exhibits inhibitory effects on the TLR4/NF-kB inflammatory signaling pathway to impede the progression of HUA-induced nephritis." (PMID 39101136, 2024). "The influx of bacteria and LPS into the circulation can activate innate immune cells through a toll-like receptor 4 (TLR4)-dependent mechanism, leading to kidney inflammation." (PMID 36832398, 2023). "Extracellular HMGB1 has been reported to increase macrophage inflammation and is highly correlated with histopathological features of renal injury in active nephritis via the TLR4/MyD88/NF-κB/p65 signaling pathway in LN." (PMID 37872565, 2023). "The results of the present study showed that the E. ulmoides leaf extract down-regulated renal expression of TLR4, a protein related to kidney inflammation, and thereby showed anti-inflammatory activity in rats on HFFD." (PMID 35656068, 2022). "The results of this study also found that lycopene can alleviate high-fat diet-induced nephritis in mice, mainly by regulating the expression of the TLR4/MyD88 pathway and its downstream inflammatory factors." (PMID 36230117, 2022). "Here, CM inhibited the expression of the TLR4/MyD88/NF-κB signaling pathway, which was in consistence with a previous report showing that CM fruit body extract relieved nephritis by inhibiting the TLR4/NF-κB signaling pathway." (PMID 35369439, 2022). "In order to further verify the effect of lycopene on the TLR4 pathway in nephritis mice from the protein level, we investigated the protein levels of TLR4, TRIF, MyD88, and NF-κB." (PMID 36230117, 2022). "A TLR4-dependent pathway promoting renal injury and inflammation in antibody-mediated glomeruli-nephritis and cisplatin-induced nephrotoxicity has also been described." (PMID 25182709, 2014). "This led us to concern that the inflammatory injury of nephritis in LN may be closely related to the activation of TLR4/MYD88 pathway mediated by NETs." (PMID 41208960, 2025). "Concurrently, it inhibited the mRNA expression of renal inflammatory cytokines via the inhibition of NLRP3/Caspase-1 and TLR4/MyD88/NF-κB signaling pathways, thereby alleviating the HUA-induced kidney inflammation." (PMID 41300001, 2025). "Pristane has been shown to induce aberrant expression of pathogen recognition receptors, namely, toll-like receptors (TLRs) including TLR4 and TLR9, in the kidney, and these TLRs are necessary for the development of pristane-induced nephritis." (PMID 32265909, 2020).
pulmonary hypertension (13 papers, 2014 to 2025). Increased pressure within the pulmonary circulation due to lung or heart disorder. "Tlr-4 deficient mice were shown to be resistant to chronic hypoxia-induced pulmonary hypertension by attenuating the pulmonary vascular inflammatory response to hypoxia." (PMID 24722050, 2014). "It has been proposed that pulmonary arterial endothelial cell ferroptosis mediates the progression of pulmonary hypertension through the MCT-induced HMGB1/TLR4/NLRP3 inflammasome signaling pathway in rats." (PMID 38111578, 2023). "Previous studies showed that TLR4 signaling involved in a variety of inflammatory and hypoxic conditions, including atherosclerosis, reperfusion injury, cardiac hypertrophy, pulmonary hypertension, and sepsis." (PMID 35832490, 2022). "Pharmacological experiments also showed that geniposide can protect pulmonary artery smooth muscle from lipopolysaccharide damage by affecting the tlr-4/myd88 signalling pathway, improve pulmonary function, and avoid the formation of pulmonary hypertension." (PMID 35356238, 2022). "The findings of these studies suggest that the role of TLR4 in mediating pulmonary hypertension is controversial and complex." (PMID 29137270, 2017). "However, the mechanism is clearly complicated as conversely, TLR4 knockout mice spontaneously develop pulmonary hypertension and increased pulmonary artery wall thickness." (PMID 38255274, 2024). "For example, some studies reported that TLR4 deletion could prevent mice from hypoxia-induced pulmonary hypertension (PH) and vascular wall thickening." (PMID 35832490, 2022). "Genetic deletion of TLR4 on platelets in mice attenuates hypoxia-induced pulmonary hypertension." (PMID 36296961, 2022). "Furthermore, it was reported that genetic deletion of TLR4 attenuated chronic hypoxia‐induced pulmonary hypertension." (PMID 32860486, 2020). "Thus, intratracheal human MSC transplantation ameliorates pulmonary hypertension, probably by suppressing TLR4 expression in newborn rats." (PMID 29137270, 2017). "In other studies using MCT to establish a rat model of pulmonary hypertension (PH), peroxiredoxin 6 (PRDX6) was found to regulate ferroptosis in PAECs through HMGB1 release and activation of the TLR4/NLRP3 inflammasome signaling pathway." (PMID 38111578, 2023). "For example, male SHR showed a higher serum mitochondrial DNA (TLR9 DAMP) when compared to females; likewise, in an animal model of pulmonary arterial hypertension, males showed a higher circulating HMGB1 (TLR4 DAMP) when compared to females." (PMID 35822020, 2021).
respiratory infection (13 papers, 2008 to 2025). "Oxidized phospholipids inhibitors were reported to ameliorate CS in humanized animal models of respiratory infections by decreasing the release of cytokines/macrophages in pulmonary tissue via the Toll-like receptor 4 (TLR4) and simultaneously causing induction of INF-γ signaling pathway." (PMID 38694122, 2024). "Therefore, further studies in TLR4 reactivated mice are warranted to verify their susceptibility to respiratory infections." (PMID 33318075, 2021). "In this pursuit, we found that, at likely more clinically-relevant inoculums, tlr4 mutant mice maintain long-term respiratory infections by A. baumannii." (PMID 40817088, 2025). "A previous report also indicated decreased levels of Prevotella after a respiratory infection, which antagonized the LPS produced by H. influenzae and inhibited the Toll-like receptor 4 (TLR4) mediated mucosal inflammation." (PMID 29232879, 2017). "In an acute model of Mtb respiratory infection, TLR2-/- and TLR4-/- mice showed increased susceptibility during early stages of infection, while macrophages from these mutant mice displayed reduced induction of antibacterial activities upon Mtb infection." (PMID 23448601, 2013). "Collectively, these data suggest that TLR4 limits respiratory infection and systemic spread of vaccinia virus." (PMID 18802464, 2008). "TLR4 is well-known as a PRR involved in acute lung injury of respiratory infection." (PMID 31958320, 2020). "Our present results show that Tlr5−/− mice are more susceptible to B. pseudomallei in a model of respiratory infection, in contrast to deficiency in Tlr2, which actually confers resistance, or Tlr4, which has no apparent effect on survival." (PMID 25232720, 2014). "Furthermore, the broad clinical phenotype of recurrent respiratory infections, and our in vitro TLR data, indicated a central role for CD14 in innate immune signaling that extends beyond TLR4." (PMID 35429403, 2022). "Following respiratory infection with vaccinia, mice lacking TLR4 signaling had greater viral replication, hypothermia, and mortality than control animals." (PMID 18802464, 2008).
retinal ischemia (13 papers, 2010 to 2024). A ischemic disease that involves the retina. "It is demonstrated that retinal ischemia not only directly induces RGCs death but also triggers damage-associated molecular pattern (DAMP)-induced toll-like receptor 4 (TLR4) inflammasome-dependent neuroinflammation to activate the microglia, thus inducing further RGCs death." (PMID 32295623, 2020). "To investigate the role of Tlr4 in retinal ischemia, we took advantage of Tlr4-deficient mice." (PMID 21031135, 2010). "Retinal ischemia/reperfusion increases Toll-like receptor 4 (TLR4) expression, triggering caspase-8 signaling." (PMID 38674050, 2024). "A study using a retinal ischemia/reperfusion (RIR) injury rat model provided further support for TLR4-induced activation of NLRP3 and also found that inhibition of TLR4 decreased loss of RGCs." (PMID 35047535, 2021). "TLR4 can lead to an increased caspase 8 expression in a retinal ischemia-reperfusion model, which is in accordance with our study results." (PMID 32833183, 2021). "The activation of NLRP inflammasomes through TLR4 activation has been demonstrated in a retinal ischemia–reperfusion injury model induced by ligation of retinal blood vessels in rat." (PMID 27822213, 2016). "We previously demonstrated that TLR4 promoted the activation of NLRP3 inflammasome which involves in the inflammatory injury of retinal ischemia." (PMID 26224068, 2015). "We induced unilateral retinal ischemia in WT and Tlr4 knockout (Tlr4 KO) mice by raising IOP above normal systolic levels and evaluating neuronal survival." (PMID 21031135, 2010). "Because of many parallels in cell death mechanisms in brain and retinal ischemia, we hypothesized that Tlr4 signaling is involved in retinal damage and in inflammation triggered by ischemic injury." (PMID 21031135, 2010). "We investigated whether retinal ischemia and inflammation produced by raising the intraocular pressure above normal systolic levels differs in mice that lack a functional toll-like receptor 4 (Tlr4) signaling pathway." (PMID 21031135, 2010). "TLR4 activation is an essential contributor in neonatal diseases, including ROP, and retinal ischemia." (PMID 39195259, 2024). "In rodents, this compound has been shown to suppress endotoxin induced ocular inflammation as well as Toll-like receptor 4 (TLR4) mediated inflammatory response and retinal damage occurring after retinal ischemia." (PMID 26180583, 2015). "However, this receptor signaling is not compatible with ProTα preconditioned via a TLR4-TRIF system in the retinal ischemia–reperfusion model." (PMID 36766838, 2023).
sickle cell disease (13 papers, 2015 to 2025). Sickle cell anemias are chronic hemolytic diseases that may induce three types of acute accidents: severe anemia, severe bacterial infections, and ischemic vasoocclusive accidents (VOA) caused by sickle-shaped red blood cells obstructing small blood vessels and capillaries. "Release of heme in a murine model of sickle cell disease induces TLR4-dependent inflammation in endothelial cells." (PMID 37991487, 2024). "Recent evidence indicates that hemolysis in sickle cell disease (SCD) promotes inflammation via innate immune signaling through toll-like receptor 4 (TLR4)." (PMID 33841413, 2021). "Triggering toll-like receptor (TLR4), heme is an established propagator of vaso-occlusion and the acute chest syndrome in mouse models of sickle cell disease." (PMID 33763072, 2021). "A study using a murine sickle cell disease model showed that heme‐mediated TLR4 signaling activates vaso‐occlusion." (PMID 34042301, 2021). "heme activates TLR-4 signaling leading to vaso-occlusion due to degranulation of Weibel-Palade bodies and expression of vascular adhesion molecules in models of sickle cell disease." (PMID 33414780, 2020). "This heme-mediated TLR4-dependent mechanism has been connected to vaso-occlusive crisis in sickle cell disease." (PMID 32695110, 2020). "It has also been reported that free heme induces oxidative free radicals, leading to severe microvascular damage in sickle cell disease through induction of TLR4." (PMID 26555697, 2015). "Accordingly, a previous study on sickle cell anemia demonstrated that the use of sodium nitroprusside could indirectly inhibit the TLR4 activation and reduce inflammatory responses and ROS (reacive oxygen species) levels." (PMID 40666114, 2025). "Persistent TLR4 signaling is responsible for chronic and acute inflammatory disorders, including sepsis, atherosclerosis, rheumatoid arthritis, acute and chronic lung injury, sickle cell disease, neurodegenerative diseases, and cancer." (PMID 38077393, 2023). "Heme, released from red blood cells in sickle cell disease (SCD), interacts with toll-like receptor 4 (TLR4) to activate NF-κB leading to the production of cytokines and adhesion molecules which promote inflammation, pain, and vaso-occlusion." (PMID 33542720, 2020).
viral myocarditis (13 papers, 2016 to 2025). Myocarditis that is caused by an infection with a viral agent. "The SARS-CoV-2 virus may lead to aberrant TLR4 downstream cellular signalling to cause cardiac injury (viral myocarditis) and lung injury, by altering the balance between MyD88-dependent and independent signalling, given the role of TLR4 in mediating abnormal inflammation and pathological fibrosis." (PMID 33505220, 2021). "Another study showed that in a viral myocarditis model, TLR4 overexpression enhanced ferroptosis, while TLR4 inhibition alleviated it." (PMID 39852551, 2025). "All of the miRs enriched in PEV had reported roles in the literature that inhibited specific pathways known to be involved in the pathogenesis of viral myocarditis including reducing viral replication, TLR4 signaling, inflammasome/NLRP3, and IL-1β." (PMID 39835120, 2024). "Less attention was paid to the role of TLR4 in viral myocarditis, presumably given the fact that TLR4 is expressed on the cell surface and only recognises distinct virus-specific components." (PMID 34072044, 2021). "This iOGN is present in circulating and cardiac innate immune cells where it boosts TLR4 signaling, as in viral myocarditis and septic shock." (PMID 27878326, 2017). "It reduces ROS production and the secretion of IL-1β to alleviate inflammation associated with metabolic disturbance in murine RAW 264.7 or J774A.1 macrophages; it suppresses plasma TLR4 expression and myocardium inflammatory cell infiltration from mice with viral myocarditis." (PMID 35774377, 2022). "Also in patients with ‘idiopathic’ DCM, a potential consequence of viral myocarditis, focal areas of increased, intense TLR4 staining in the heart have been described." (PMID 34072044, 2021). "Next, we wondered whether the lack of this OGN–TLR4 interaction may influence cardiac inflammation as lack of TLR4 signaling during viral myocarditis has previously been associated with decreased cardiac inflammation." (PMID 27878326, 2017). "In viral myocarditis (VMC), specifically induced by Coxsackievirus B3 (CVB3), evidence suggests that TLR4 plays a significant role." (PMID 38790263, 2024). "Lupeol downregulated the mRNA and protein expressions of TLR4 with the inhibition of the downstream MyD88 and NF-κB, restraining the release of IL-1β and TNF-ɑ, in viral myocarditis mice." (PMID 34777686, 2021). "Aside from influencing cardiac inflammation in viral myocarditis, the interaction of OGN with TLR4 may also influence the development and progression of other cardiac diseases." (PMID 27878326, 2017).
acute coronary syndrome (12 papers, 2011 to 2026). Signs and symptoms related to acute ischemia of the myocardium secondary to coronary artery disease. "The examination of additional groups of patients, such as acute coronary syndrome and overt HF, are required to further clarify the role of TLR4 in being the cause of or a marker for those conditions." (PMID 26030867, 2015). "The human TLR4 polymorphisms Asp299Gly and Thr399Ile impair receptor function, and have been linked to a strong increase in acute coronary syndrome." (PMID 21513697, 2011). "Increased expression of TLR-2 and TLR-4 was observed in monocytes from patients with angina and acute coronary syndrome." (PMID 25329057, 2014). "Prior studies have demonstrated the increased expression of TLR2 and TLR4 on monocytes from patients with angina and acute coronary syndrome." (PMID 21698167, 2011). "TLR4 mRNA expression was higher than TLR2 mRNA expression in plaque debris from older adults, and acute coronary syndrome patients showed higher plaque TLR4 expression than patients with stable angina, suggesting that increases in TLR4 expression may contribute to plaque instability during aging." (PMID 35822020, 2021).
bone cancer (12 papers, 2010 to 2025). A primary or metastatic malignant neoplasm affecting the bone or articular cartilage. "TLR4 siRNA439 treatment caused a significant decrease (n = 4, ANOVA1w, P < 0.01, post hoc Dunnett testing) relative to the level in mismatch siRNA- and vehicle-treated bone cancer pain rats, and a significant decline compared to normal rats(P < 0.05) in the IBCP group." (PMID 20089147, 2010). "In bone cancer, OT alleviates bone cancer pain by inhibiting the upregulation of TLR4, TNFα, and IL-1β in the spinal cord." (PMID 39290327, 2024). "Activation of spinal TLR4 is critical to the genesis of many pathological pain conditions like those induced by nerve injury, bone cancer, peripheral tissue inflammation induced by complete Freund’s adjuvant, and opioid-induced hyperalgesia." (PMID 25571780, 2015). "LvOn-siTLR4 with DOX was intrathecally delivered into the rats with bone cancer pain and protein expressions of TLR4 and its mRNA were detected." (PMID 26556957, 2015). "In this study, the effects of nociception on bone cancer pain models were investigated by inducible lentivirus expressing siRNA against TLR4." (PMID 26556957, 2015). "A promising treatment for bone cancer pain is the downregulation of TLR4 by RNA interference; however, naked siRNA (small interference RNA) is not effective in long-term treatments." (PMID 26556957, 2015). "TLR4 and its mRNA expressions were decreased in the LvOn-siTLR4 with DOX group compared with that in other four groups of bone cancer pain, suggesting that lentivirus expressed small RNA of TLR4 interfered TLR4 expression." (PMID 26556957, 2015). "Pharmacological blockade of spinal TLR4 prevents and rapidly reverses allodynia in rodents with neuropathic pain, bone cancer pain, or inflammatory pain induced by complete Freund’s adjuvant." (PMID 25571780, 2015). "Our study provided a new approach of bone cancer pain treatment by downregulation of TLR4 expression using an inducible lentivirus LvOn-siTLR4." (PMID 26556957, 2015). "Although bone cancer pain is still not fully understood by scientists and clinicians alike, studies suggest that toll like receptor 4 (TLR4) plays an important role in the initiation and/or maintenance of pathological pain state in bone cancer pain." (PMID 26556957, 2015). "Similar results were shown in the protein expression, which suggested that TLR4 increased in the bone cancer pain models." (PMID 26556957, 2015). "Activation of spinal TLR4 plays a critical role in the genesis of pathological pain induced by nerve injury, bone cancer, and tissue inflammation." (PMID 25571780, 2015). "The present study was designed to investigate the role of spinal Toll-like receptor 4 (TLR4) induced glial neuroinflammation in cancer induced pain using a modified rat model of bone cancer." (PMID 22607655, 2012). "The bone cancer pain rats treated with TLR4 siRNA displayed significantly attenuated behavioral hypersensitivity and decreased expression of spinal microglial markers and proinflammatory cytokines compared with controls." (PMID 20089147, 2010). "Our data showed that the spinal microglial activation markers mRNA, TLR4 mRNA and TLR4 protein expression were significantly elevated in the rat model of bone cancer pain." (PMID 20089147, 2010). "We established a role for TLR4 and CNS innate neuroimmune activation in the development of behavioral hypersensitivity in a rat model of bone cancer pain." (PMID 20089147, 2010). "In a complementary study, TLR4 small interfering RNA(siRNA) was administered intrathecally to bone cancer pain rats to reduce the expression of spinal TLR4." (PMID 20089147, 2010). "Our results provide evidence for a role of the key innate immune receptor, TLR4, in a rat model of bone cancer pain." (PMID 20089147, 2010).